ELN (elastin)
Diseases named in the same sentence as ELN in open-access papers (continued):
Sharing a sentence is not in itself a finding about the gene and the disease.
anxiety disorder (1 paper, 2021). A category of psychiatric disorders which are characterized by anxious feelings or fear often accompanied by physical symptoms associated with anxiety. "Phenotype genotype correlation is poor, except for involvement of elastin and Gtf2i genes showing increased risk of aortic dilatation and anxiety disorder, respectively." (PMID 33269527, 2021).
aortitis (1 paper, 2025). Inflammation of the aorta. "In aortitis, PR3-ANCA triggers neutrophil degranulation, releasing cytokines (e.g., TNF-alpha and IL-1) and MMPs that degrade elastin and collagen in the aortic media, causing inflammatory weakening." (PMID 40535417, 2025). "In GPA and MPA, PR3-ANCA or MPO-ANCA-mediated neutrophil activation causes aortitis by releasing cytokines (e.g., tumor necrosis factor (TNF)-alpha and IL-1) and matrix metalloproteinases (MMPs) that degrade elastin and collagen in the aortic media, weakening the vessel wall." (PMID 40535417, 2025).
Arrhythmia (1 paper, 2023). Any cardiac rhythm other than the normal sinus rhythm. "When the HR increases, it can put individuals in danger of arrhythmias and lead to higher cyclic stretch and elastin fatigue." (PMID 37504536, 2023).
arterial occlusive disease (1 paper, 2015). Pathological processes which result in the partial or complete obstruction of ARTERIES. "In elastin knockout mice, fatal arterial occlusive disease results from uncontrolled proliferation of vascular smooth muscle cells (VSMCs), suggesting a critical role for elastin in VSMC inhibition, consistent with recent in vitro findings." (PMID 26115013, 2015).
Ascites (1 paper, 2025). Accumulation of fluid in the peritoneal cavity (between the layers of the peritoneum that lines the abdomen). "The BCM is the overall cell mass, which is metabolically active and therefore responsible for the metabolic rate; the ECM includes interstitial water (ascites, pleural effusion, and so on) and connective tissues such as collagen, elastin, skin, tendons, and bone." (PMID 39861464, 2025).
astrocytoma (1 paper, 2022). "The astrocytoma cells were able to penetrate and migrate through the intact elastin membrane and degrade elastin." (PMID 34374904, 2022). "It has been described to date that, in human astrocytoma cell lines (U87 MG, U251 MG, and U373 MG), κ-elastin increases the number of cells penetrating and migrating through an intact elastin membrane." (PMID 34374904, 2022). "It was shown that the presence of elastin-degradation products increased the invasive potential of cultured astrocytoma cells seeded on organotypic cultures of brain slices." (PMID 34374904, 2022). "The invasive potential tested in the described model was significantly increased after exposure to κ-elastin, which interacted with EBP on the surface of astrocytoma cells." (PMID 34374904, 2022).
autism (1 paper, 2018). Persistent deficits in social interaction and communication and interaction as well as a markedly restricted repertoire of activity and interest as well as repetitive patterns of behavior. "However, one prior study found weak associations between this SNP and autism, though ELN has minimal expression in the human brain." (PMID 29614955, 2018).
autonomous disorder (1 paper, 2012). "Consistent with a cell autonomous disorder, SMARCAL1 was expressed in arterial and lung tissue, and both the aorta and lung of SIOD patients had reduced expression of elastin and alterations in the expression of regulators of elastin gene expression." (PMID 22998683, 2012).
autosomal recessive cutis laxa type 2A (1 paper, 2023). An autosomal recessive cutis laxa type II classic type that has material basis in homozygous or compound heterozygous mutations in the ATP6V0A2 gene on chromosome 12q24. "ATP6VOA2 proton pump mutations in autosomal recessive cutis laxa type 2A (ARCL2A) cause increased cellular apoptosis and elastin networks are fragmented into clumps." (PMID 37001705, 2023).
bladder cancer (1 paper, 2024). "We found that TNFRSF12A, IL1R1, ELN and CYP26B1 were overexpressed in bladder cancer cell lines, while NR1H3 and ITIH4 were downregulated." (PMID 38216619, 2024).
bladder tumour (1 paper, 2016). "We suggest from this research that studying the relative changes in elastin and collagen compared to NADH and flavins may serve as a useful tool for monitoring bladder tumour development." (PMID 27446646, 2016).
brain injury (1 paper, 2022). Acute and chronic (see also brain INJURIES, CHRONIC) injuries to the brain, including the cerebral hemispheres, CEREBELLUM, and brain STEM. "Elastin-derived peptides (EDPs), the fragmented product of elastin protein, have been implicated in the progression of neurological degeneration during acquired brain injury." (PMID 36140268, 2022).
CADASIL (1 paper, 2023). "Interestingly, the presence of elastin in arterioles but not capillaries could provide an explanation for the functional presence of Kir2.1 in arterioles but not capillaries of mice with cerebral autosomal dominant arteriopathy with subcortical infarcts and leukoencephalopathy (CADASIL)." (PMID 37855433, 2023).
calcinosis (1 paper, 2024). Deposition of calcium in the tissues. "The histopathologic examination of calcinosis deposits from SSc patients has demonstrated disorganized collagen fibers and elastin, an increase in the number of fibrocytes, and fibrotic changes, around the calcinosis." (PMID 39457038, 2024).
cholestasis (1 paper, 2018). Impairment of the bile flow caused by obstruction within the liver, or outside the liver in the bile duct system. "Its higher than normal expression in GWI animals could prevent metalloproteinases from degrading the increased amount of collagen, elastin and other extracellular matrix proteins produced by HSCs due to BDL-induced cholestasis in our animal model." (PMID 30177688, 2018).
coronary aneurysm (1 paper, 2016). Abnormal balloon- or sac-like dilatation in the wall of coronary vessels. "These, together with high levels of MMP-9 that can break down elastin in coronary artery walls, promote the development of coronary aneurysms during the pathogenic process of KD." (PMID 27800490, 2016).
cyst (1 paper, 2016). A sac-like closed membranous structure that may be empty or contain fluid or amorphous material. "It is also reported that histologically nonspecific interstitial pneumonitis may be seen as well as paucity of elastin tissue in the walls of cyst." (PMID 27781131, 2016).
dermatophytosis (1 paper, 2019). A common fungal infection of the stratum corneum of the skin, hair, or nails by a dermatophyte. "The fungal thioredoxin was induced by superficial (keratin) and deep (elastin) skin elements suggesting that the product of this gene could be important in superficial and deep dermatophytosis." (PMID 31795354, 2019).
duodenal atresia (1 paper, 2023). Duodenal atresia is an embryopathy of the cranial intestine that leads to a complete absence of the duodenal lumen. "Pathogenic evidence is needed to be provided to prove the causative effect of elastin deficiency and duodenal atresia." (PMID 37422671, 2023).
endocarditis (1 paper, 2025). Inflammation of the endocardium. "The role of fibronectin-binding protein A (FnBPA) in this context has been demonstrated to be crucial in facilitating a synthesis between these two specific properties, in conjunction with the binding of elastin, thereby promoting experimental endocarditis." (PMID 40422904, 2025).
epidermolysis bullosa (1 paper, 2025). Epidermolysis bullosa (EB) is a group of genetic skin diseases that cause the skin to blister very easily. "Analysis of this region using live imaging could advance the development of mechanisms and treatments related to the binding between COLVII and elastin fibers, epidermolysis bullosa, and wound healing." (PMID 40102595, 2025).
epilepsy (1 paper, 2021). A brain disorder characterized by episodes of abnormally increased neuronal discharge resulting in transient episodes of sensory or motor neurological dysfunction, or psychic dysfunction. "As NE is involved in immune responses and widely regarded as a regulatory factor in degenerative and inflammatory diseases through proteolysis of collagen-IV and elastin, ELANE may be also associated with epilepsy." (PMID 34555062, 2021).
esophageal squamous cell carcinoma (1 paper, 2023). Esophageal squamous cell carcinoma (ESCC) is a type of esophageal carcinoma (EC) that can affect any part of the esophagus, but is usually located in the upper or middle third. "However, few studies have investigated the LVI positivity rate and its clinical significance in pT1b esophageal squamous cell carcinoma (ESCC) using immunohistochemistry and elastin staining." (PMID 37087442, 2023).
esophagitis (1 paper, 2020). An acute or chronic inflammatory disease affecting the esophageal wall. "Such lifetime differences may be attributed to increased connective tissue (e.g., collagen and elastin) associated with esophagitis." (PMID 32477151, 2020).
Fabry disease (1 paper, 2014). Fabry disease (FD) is a progressive, inherited, multisystemic lysosomal storage disease characterized by specific neurological, cutaneous, renal, cardiovascular, cochleo-vestibular and cerebrovascular manifestations. "In Fabry disease, storage of glycosphingolipids takes place in vascular endothelial and smooth muscle cells, and in MPS I, accumulation of glycosaminoglycans in the connective tissue of the aortic wall impairs the formation of elastin and leads to changes in collagen formation." (PMID 24407465, 2014).
gastric cancer (1 paper, 2022). A primary or metastatic malignant neoplasm involving the stomach. "Studies have shown that desmin (DES) protein is more advantageous than elastin protein in detecting vascular invasion in gastric cancer and is considered one of the markers of tumor invasion." (PMID 36467074, 2022).
gastroesophageal reflux (1 paper, 2018). "We speculate that in disease states in which gastroesophageal reflux is prevalent and possibilities of aspiration into the lung are high, the cascade of events triggered by gastric contents aspiration may be an important mechanism contributing to the elastin degradation reported in these conditions." (PMID 30170599, 2018).
granuloma annulare (1 paper, 2013). Granuloma annulare is a long-term (chronic) skin disease consisting of a rash with reddish bumps arranged in a circle or ring. "Granuloma annulare is a benign disease of unknown etiology with a lymphocyte-mediated hypersensitivity type IV mechanism where an immunologic cell-mediated process or a primary collagen and/or elastin destruction have often been suggested." (PMID 23738153, 2013).
hamartoma (1 paper, 2023). A benign and excessive tumor-like growth of mature cells and normal tissues which grow in a disorganized pattern. "Connective tissue nevi are hamartomas of the dermis, with the three main components of collagen (collagenoma), elastin (elastoma), and proteoglycans (mucinous nevus)." (PMID 37323268, 2023). "Connective tissue nevus is a hamartoma composed of excess amounts of one or several components of the dermis, such as collagen, elastin, and proteoglycans." (PMID 37323268, 2023).
head and neck squamous cell carcinoma (1 paper, 2020). A squamous cell carcinoma that arises from any of the following anatomic sites: lip and oral cavity, nasal cavity, paranasal sinuses, pharynx, larynx, and salivary glands. "LOXL4 encodes a copper-dependent amine oxidase that is involved in the formation of crosslinks in collagens and elastin and is a potential drug target for the treatment of head and neck squamous cell carcinoma, where it is differentially expressed between tumor and normal tissue." (PMID 32727620, 2020).
HELLP syndrome (1 paper, 2015). A life-threatening condition that can potentially complicate pregnancy. "HELLP syndrome induces a decrease in the elastin content accompanied by thickening of the vessel wall in umbilical cord arteries." (PMID 26019650, 2015).
hepatocellular adenoma (1 paper, 2004). A benign epithelial neoplasm arising from the hepatocytes. "In hepatocellular adenoma, another benign condition of hepatocytic proliferation associated with an irregular and abnormal vascularization, both elastin and fibrillin-1 immunostaining pointed to the great number of vascular sections distributed inside the tumor." (PMID 14960209, 2004). "Immunohistochemical studies for fibrillin-1 and elastin were performed on unfixed cryostat sections of focal nodular hyperplasia (22 cases), hepatocellular adenoma (15 cases) and surrounding liver (34 cases)." (PMID 14960209, 2004). "Therefore, in this work, the expression and distribution of fibrillin-1 and elastin were studied in hepatic focal nodular hyperplasia and compared with surrounding liver and hepatocellular adenoma." (PMID 14960209, 2004).
hereditary hemorrhagic telangiectasia (1 paper, 2024). A disorder of angiogenesis leading to arteriovenous dilatations: cutaneo-mucosal hemorrhagic telangiectasias and visceral shunting. "Hereditary hemorrhagic telangiectasia (HHT) is an autosomal dominant disorder with variable penetrance that leads to progressive loss of elastin from the blood vessel walls." (PMID 39262767, 2024).
hyperuricemia (1 paper, 2023). An abnormally high level of uric acid. "We found that hyperuricemia itself increased the expansion of the diameter of the abdominal aorta, the incidence of AAA and the degradation of elastin fibers in the aorta in ApoE-KO mice." (PMID 36710339, 2023). "Hyperuricemia also enhanced Ang II-induced AAA formation, abdominal aortic diameter expansion and elastin fiber degradation, which suggests roles for hyperuricemia in the pathogenesis of AAA." (PMID 36710339, 2023). "In our study, mice with hyperuricemia alone that were not treated with Ang II presented increased aortic diameters, exacerbated elastin degradation, and elevated MMP-9 protein levels." (PMID 36710339, 2023).
Hypoalbuminemia (1 paper, 2025). The concentration of albumin in the blood circulation is below the lower limit of normal. "Malnutrition-induced hypoalbuminemia and oxidative stress likely impair endothelial nutrient transport, exacerbating medial hypoxia, and elastin fragmentation." (PMID 40917092, 2025).
idiopathic pulmonary arterial hypertension (1 paper, 2020). A sporadic form of pulmonary arterial hypertension (PAH) characterized by elevated pulmonary arterial resistance leading to right heart failure. "In PA tissues of non-PH, PAH-CHD, and idiopathic pulmonary arterial hypertension (IPAH) patients, we investigated PA remodeling and the regulation of ECM (e.g., collagen and elastin)." (PMID 32630068, 2020).
Impaired glucose tolerance (1 paper, 2014). An abnormal resistance to glucose, i.e., a reduction in the ability to maintain glucose levels in the blood stream within normal limits following oral or intravenous administration of glucose. "Further, individuals with WS with half-normal elastin levels are at higher risk of developing impaired glucose tolerance." (PMID 26167199, 2014).
infertile (1 paper, 2024). "Previous studies of common dolphins (Delphinus delphis) have suggested that the relative content of elastin in small CAs may be used as a guide to whether a given corpus resulted from a pregnancy or an infertile ovulation." (PMID 38968179, 2024).
inflammatory bowel disease (1 paper, 2023). A spectrum of small and large bowel inflammatory diseases of unknown etiology. "Chronic inflammation in inflammatory bowel disease (IBD) triggers significant extracellular matrix remodeling, including elastin remodeling, leading to severe clinical complications." (PMID 38202027, 2023).
interstitial cystitis (1 paper, 2025). A rare chronic debilitating urogenital disease characterized by urinary frequency, urgency, and pelvic pain. "Prior histopathological studies in feline interstitial cystitis have described suburothelial proliferation, immune cell infiltration, von Brunn’s nests, neovascularization, elastin remodeling, and increased COX-2 expression in the proximal urethra." (PMID 41169683, 2025).
intrauterine growth restriction (1 paper, 2022). "Animal models of intrauterine growth restriction demonstrated an altered elastin to collagen ratio (with less elastin and increased collagen engagement, which is 100–1000 times stiffer than elastin), which in turn led to increased arterial stiffness." (PMID 35207646, 2022).
leiomyoma (1 paper, 2023). A well-circumscribed benign smooth muscle neoplasm characterized by the presence of spindle cells with cigar-shaped nuclei, interlacing fascicles, and a whorled pattern. "Under the traction of huge leiomyoma, as well as the loss of collagen and elastin with the growth of age, the uterine ligaments are progressively stretched, with the firmness reduced." (PMID 37960802, 2023).
lichen planus (1 paper, 2025). A chronic, recurrent, pruritic inflammatory disorder of unknown etiology that affects the skin and mucus membranes. "AALP is the rarest variant of lichen planus, distinguished by a reduction of elastin fibers in the superficial dermis." (PMID 39742325, 2025). "Annular atrophic lichen planus (AALP) is an exceedingly rare variant of lichen planus, characterized by annular plaques with central atrophy and a reduction of elastin fibers in the superficial dermis." (PMID 39742325, 2025).
limb ischemia (1 paper, 2021). A ischemia that involves the limb. "The case-control design on diabetic patients ulcers as case group and non-diabetic limb ischemia as control were used.Hematoxylin-eosin, trichrome, and elastin staining methods were used for pathological evaluations of ECM." (PMID 34095552, 2021).
lymphangioleiomyomatosis (1 paper, 2008). A multifocal neoplasm with perivascular epithelioid cell differentiation affecting almost exclusively females of child-bearing age. "A reciprocal relationship between versican and elastin and EBP has been previously demonstrated for vascular and dermal tissues, and also for the rare lung condition lymphangioleiomyomatosis." (PMID 18485243, 2008).
malnutrition (1 paper, 2025). Inadequate nutrition resulting from poor diet, malabsorption, or abnormal nutrient distribution. "Malnutrition can result in inadequate protein synthesis and energy deficiency, leading to the gradual breakdown of elastin and other detrimental changes in the vascular walls." (PMID 40917092, 2025).
medulloblastoma (1 paper, 2024). A malignant, invasive embryonal neoplasm arising from the cerebellum. "Forms microfibrils that serve as a scaffold for elastin deposition, increasing tissue elasticity.Increased together with lumicans, specifically in medulloblastomas." (PMID 38994941, 2024).
meningioma (1 paper, 2024). A generally slow growing tumor attached to the dura mater. "The case of meningioma was further characterized by the presence of fiber-like as well as of round fluorescent structures, presumably elastin fibers and psammoma bodies." (PMID 39724474, 2024).
meningocele (1 paper, 2022). A congenital abnormality in which the meninges protrude through a defect in the spinal column or the cranium. "Moreover, we found a canonical splice site mutation NM_000501.3:c.2032 + 1G > A in elastin (ELN) in P37 with microcephaly and meningocele." (PMID 35562572, 2022).
metastasis (1 paper, 2018). The spread or migration of cancer cells from one part of the body (where they first appeared) to another. "In the RNA sequencing data genes linked to arteries (Elastin, Lamb1, Acta2), pericytes (Cspg4/Ng2, Pdgfrb, Sca1 (Ly6a)) and neurons/neurites (Gap43, Tubb3) were up-regulated in the stroma of osteolytic bone metastasis." (PMID 29988965, 2018).